VIT (vitrin)
Description:
Promotes matrix assembly and cell adhesiveness. Plays a role in spinal cord formation by regulating the proliferation and differentiation of neural stem cells.
Synonyms: VIT1
Tractability: Antibody: UniProt places it where antibodies can reach, with medium confidence; UniProt predicts a signal peptide or a membrane-spanning region; its Gene Ontology location is reachable by antibodies, with medium confidence. PROTAC: its protein half-life has been measured.
Gene: Protein-coding gene on chromosome 2 (36,696,690 to 36,814,794, forward strand). Ensembl gene ENSG00000205221.
Subcellular location: Secreted, extracellular space, extracellular matrix
Gene Ontology:
Molecular function: glycosaminoglycan binding
Biological process: extracellular matrix organization; positive regulation of cell-substrate adhesion; spinal cord development
Cellular component: interstitial matrix; extracellular matrix
Genetic constraint (gnomAD): Loss-of-function variants: 98 observed, 79.71 expected, observed/expected ratio (o/e) 1.23, 90% interval 1.04 to 1.45. The upper end of that interval is the gene's LOEUF score, 1.45, which puts it in group 6 of 6, group 1 being the genes least tolerant of losing a copy. Missense variants: 1,118 observed, 907.11 expected, observed/expected ratio (o/e) 1.23, 90% interval 1.17 to 1.29. Synonymous variants: 372 observed, 351.13 expected, observed/expected ratio (o/e) 1.06, 90% interval 0.97 to 1.15.
Homologues: Orthologues: chimpanzee VIT (99% identical), macaque VIT (97% identical), rabbit VIT (88% identical), dog VIT (84% identical), pig VIT (83% identical), rat Vit (80% identical), mouse Vit (80% identical), guinea pig VIT (77% identical), tropical clawed frog vit (61% identical), zebrafish vit (56% identical). Paralogues in human: COL12A1 (19% identical), COL6A3 (18% identical), COL6A6 (17% identical), COL6A5 (16% identical), COL14A1 (13% identical), COCH (12% identical), MATN2 (11% identical), MATN4 (10% identical), MATN3 (10% identical), MATN1 (9% identical), VWA2 (9% identical), VWA1 (7% identical).
Diseases named in the same sentence as VIT in open-access papers:
VIT is named in the same sentence as 17 diseases in open-access papers, as found by Europe PMC text mining. Sharing a sentence is not in itself a finding about the gene and the disease. The quoted sentences say what the papers report.
breast carcinoma (3 papers, 2020 to 2023). "Our analysis of stromal changes between non-metastatic and metastatic canine mammary carcinomas highlighted molecular differences in the tumour microenvironment, including changes in VIT, TGFBR2, TGFBR3, LTBP4 and SFRP1." (PMID 37391533, 2023).
Hernia (3 papers, 2020 to 2023). "The VIT downregulation detected in the present study may disturb the production of cell adhesion proteins, reducing the integrity of the umbilical ring making this tissue more susceptible to hernia occurrence." (PMID 32379844, 2020). "Quantitative real-time PCR was performed for MMP13, VIT, ACAN, and COL6A5 in muscle and connective tissue for all 68 animals, revealing differences in the mRNA level of MMP13 and VIT between the control and hernia pigs." (PMID 37895252, 2023). "The microtubule associated protein 1 light chain 3 γ (MAP1LC3C), vitrin (VIT), aggrecan (ACAN), alkaline ceramidase 2 (ACER2), potassium calcium-activated channel subfamily M α 1 (KCNMA1) and synaptopodin 2 (SYNPO2) genes are highlighted as candidates to trigger both types of hernia." (PMID 33513662, 2021). "The results pointed out ACAN, MMPs, COLs, EPYC, VIT, CCBE1 and LGALS3 genes as strong candidates to trigger umbilical hernias in pigs, because they are involved in hernia related biological processes since the embryogenesis." (PMID 32379844, 2020).
Umbilical hernia (2 papers, 2020 to 2023). Protrusion of abdominal contents through a defect in the abdominal wall musculature around the umbilicus. "The VIT gene differed in transcript level in muscle tissues, which may be a result of umbilical hernia, rather than a cause." (PMID 37895252, 2023). "The results pointed out ACAN, MMPs, COLs, EPYC, VIT, CCBE1 and LGALS3 as strong candidates to trigger umbilical hernias in pigs since they act in the extracellular matrix remodeling and in the production, integrity and resistance of the collagen." (PMID 32379844, 2020).
Alzheimer disease (1 paper, 2019). A progressive, neurodegenerative disease characterized by loss of function and death of nerve cells in several areas of the brain leading to loss of cognitive function such as memory and language. "Finally, in the broader context of traits potentially related to cognition, we find an enrichment of HHMCs in genes associated to “Alzheimer’s disease (cognitive decline)” and “Cognitive decline (age-related)”, with seven associated genes (COX7B2, BCAS3, DMXL1, LIPC, PLEKHG1, TTLL2 and VIT)." (PMID 31186485, 2019).
osteoarthritis (1 paper, 2025). A noninflammatory degenerative joint disease occurring chiefly in older persons, characterized by degeneration of the articular cartilage, hypertrophy of bone at the margins and changes in the synovial membrane. "LOF + MIS variants in ADAMTS6, SPRY2 and COLGALT2 are protective against osteoarthritis, whereas aggregation of these variants in ADAMTSL3, VIT, IL11 and THBS3 confer risk of osteoarthritis." (PMID 40205036, 2025).
tumour (3 papers, 2014 to 2023). "This cluster included six PR proteins including two tumour-related proteins (VIT_17s0119g00150 and VIT_17s0119g00230) and a number of transcription factors, including GROWTH REGULTING FACTOR 3 (VIT_09s0002g01350)." (PMID 24692649, 2014). "Inasmuch as it is plausible that TAT and VIT may have direct functions in modulating the tumor immune microenvironment, it is also formally possible that these genes are under the same transcriptional regulation as the other genes in PAGES-HBC." (PMID 31618954, 2019).
cancer (2 papers, 2023 to 2025). A tumor composed of atypical neoplastic, often pleomorphic cells that invade other tissues. "We observed that a 7-day treatment with BZDRs downregulated anti-tumorigenic ECMs, S100B, COL6A6 and VIT, in both non-carcinoma (MCF10A) and carcinoma cells (MCF7 and MDA-MB231) (blue boxes, * p < 0.05; ** p < 0.01; *** p < 0.005)." (PMID 40583063, 2025).
infection (2 papers, 2017 to 2023). The state of being infected such as from the introduction of a foreign agent such as serum, vaccine, antigenic substance or organism. "High levels of VIT proteins enhance susceptibility to pathogen infection and contributes to immunosenescence." (PMID 28559483, 2017). "Although protein accumulation enhanced the UPR, which mitigated the adverse effects of accumulated VIT proteins on the isolated mutant animals, the animals exhibited enhanced susceptibility to pathogen infection and a shortened life span." (PMID 28559483, 2017). "To address whether accumulation of VIT proteins with age affects the response to infection, we studied the pathogen susceptibility of aging animals upon knockdown of vit genes." (PMID 28559483, 2017). "Although some genes such as photosystem II protein D1 (VIT_13s0019g02630) and chloroplastic calvin cycle protein CP12-3 (VIT_18s0122g00460) showed increases in expression in infected leaves, the infection actually reduced plant photosynthesis." (PMID 36834661, 2023).
VIT also shares sentences with these, for which no sentence is quoted: adenoma (2 papers); chronic kidney disease (1); cognitive decline (1); diabetes (1); diabetic retinopathy (1); hip osteoarthritis (1); Hypertension (1); Inguinal hernia (1); iron deficiency (1).